VCAM1 (vascular cell adhesion molecule 1)
Diseases named in the same sentence as VCAM1 in open-access papers (continued):
Sharing a sentence is not in itself a finding about the gene and the disease.
asthma (continued). "In this study, we demonstrated that a novel human anti-VCAM-1 mAb exerted anti-inflammatory and anti-asthma effects." (PMID 23855490, 2013). "According to previous studies, VCAM-1 is up-regulated after bronchial allergen challenge in patients with asthma." (PMID 23762160, 2013). "We evaluated the anti-inflammatory effects of IV treatment with human anti-VCAM-1 mAb on the pathophysiological features of asthma via an OVA-induced acute asthma model." (PMID 23855490, 2013). "In the chronic asthma mouse model, we observed similar anti-inflammatory and anti-asthma effects for IV human anti-VCAM-1 mAb." (PMID 23855490, 2013). "According to previous studies, ICAM-1 and VCAM-1 are upregulated on the bronchial vascular endothelium after bronchial allergen challenge in patients with asthma." (PMID 23029210, 2012). "In asthma, VCAM‐1 was also increased at the bronchial arteries level only reinforcing the hypothesis that the mechanisms regulating leukocyte kinetics between pulmonary and bronchial circulation are different." (PMID 41316930, 2025). "In addition, immunohistochemistry revealed increased ICAM-1 and VCAM-1 expression in vessels in the lung tissues in mice with both ampicillin-treated D. farinae and untreated D. farinae-induced asthma." (PMID 37252681, 2023). "Our findings highlight VCAM1, EXTL2, and PANK1 as functional loci for asthma exacerbations applicable to people across different ancestral backgrounds, warranting future investigation of these novel genomic mechanisms underlying asthma exacerbations." (PMID 35754128, 2022). "Regarding biomarkers and disease control, a decreasing trend with poor asthma control was indicated for markers VCAM-1 (median 851.25 full control vs. 711.35 insufficient control; p = 0.133) and ADMA (median 0.46 full control vs. 0.40 insufficient control; p = 0.143)." (PMID 36289876, 2022). "Besides, bilirubin has also been proven to inhibit the vascular cell adhesion molecule-1-dependent lymphocyte migration and reduce airway inflammation in a murine asthma model." (PMID 36059822, 2022). "VCAM1 is involved in cancer progression and several immunological disorders, including asthma." (PMID 35754128, 2022). "Data showed that asthma induction promoted VCAM-1 levels compared to the Control group." (PMID 35209844, 2022). "VCAM-1 expression was increased only in the BA walls, suggesting that differences exist in endothelial activation between pulmonary and bronchial arteries in asthma." (PMID 31485240, 2019). "Together, these results suggest that antibodies targeting VCAM-1 may be an effective therapeutic approach to alleviate asthma." (PMID 29614819, 2018). "We attempted to evaluate whether a recently developed human anti-VCAM-1 mAb can inhibit the pathophysiological features of asthma in a murine asthma model induced by ovalbumin (OVA)." (PMID 23855490, 2013). "In this study, we tested whether a novel monoclonal antibody designed to bind human VCAM-1 molecule attenuated allergic inflammation and ameliorated the pathophysiological features of asthma in an OVA-induced murine model." (PMID 23855490, 2013). "Soluble VCAM-1 was increased in the sputa and sera of asthma patients." (PMID 23855490, 2013). "Efficient removal in severe asthma may be due to greater lung endothelial VCAM-1 expression, as has been observed in bronchial biopsies of subjects with severe compared to non-severe asthma." (PMID 23554594, 2013). "The results suggested that human anti-VCAM-1 mAb could potentially be used as an additional anti-asthma therapeutic medicine." (PMID 23855490, 2013). "Accordingly, monoclonal antibody (mAb) against VCAM-1 may attenuate allergic inflammation and pathophysiological features of asthma." (PMID 23855490, 2013). "The pathogenesis of asthma, eosinophil migration into the lung is VCAM-1 dependent." (PMID 23690670, 2013).
asthma (continued). "The stimulatory role of IL-13 on VCAM-1 may be important in asthma since VCAM-1 has been regarded as a key player in the development of airway inflammation." (PMID 15661077, 2005). "Adhesion assays with eosinophil reveal that IL-4 increases VCAM-1 expression in airway endothelial cells and results in the increased adhesion of eosinophils to VCAM-1 on the cells, emphasizing that the adhesion of eosinophil with VCAM-1 may play a central role in the pathogenesis of asthma." (PMID 29614819, 2018). "Thus, VCAM-1 could be a novel therapeutic target for several diseases characterized by eosinophilic inflammation such as asthma, allergic rhinitis and eosinophilic bronchitis." (PMID 23855490, 2013). "The results shows that eotaxin, VCAM-1, LTC4, and PGD2 levels were increased by the induction of asthma compared with those in normal mice (about 5.8-, 11.3-, 3.4-, and 2.9-fold, respectively)." (PMID 36115955, 2022). "In our study, VCAM-1 and PAI-I as two biomarkers of ED were significantly higher in children with both pneumonia and asthma than the children with pneumonia only." (PMID 36076196, 2022). "There is an increasing evidence that inflammatory proteins, such as VCAM-1, ICAM-1, cPLA2, COX-2, and MMP-9 are involved in the pathogenesis of respiratory diseases, such as asthma and COPD." (PMID 23690670, 2013). "In conclusion, human anti-VCAM-1 mAb attenuated allergic inflammation and the pathophysiological features of asthma in OVA-induced murine asthma model." (PMID 23855490, 2013). "Immunohistochemistry revealed increased VCAM-1 expression in the lung tissues of both acute and chronic OVA–induced asthma mice." (PMID 23855490, 2013). "VCAM-1 and ICAM-1 expression is known to be increased in the bronchial epithelium of asthma patients, and these cell adhesion molecules have been shown to be related to the release of eosinophil cationic protein." (PMID 23855490, 2013). "Vascular cell adhesion protein 1 (VCAM-1), a glycoprotein whose expression is induced by proinflammatory cytokines and ROS, plays a critical role in transendothelial migration of leukocytes in asthma." (PMID 41515904, 2025). "In the obese asthma model, FIP-fve markedly attenuated Der p-induced AHR and decreased serum levels of pro-inflammatory and allergic markers, including IL-6, IL-33, osteopontin, and VCAM-1." (PMID 40998975, 2025). "Furthermore, the inability of corticosteroids to reduce TNFα/IFNγ-induced VCAM1 and antigen presenting genes implicate ASM-T cell interactions in persistent airway inflammation and thickening in severe asthma." (PMID 35578269, 2022). "In addition, our previous OVA-induced asthma study revealed that increased adhesion molecules, such as ICAM-1 and VCAM-1, were found to influx inflammatory cells from the blood into the lungs." (PMID 35163544, 2022). "The connection between PARP-1 and VCAM-1 provides an insight on how PARP-1 inhibition reduces asthma-like traits without affecting DC function." (PMID 31178661, 2019). "Asthma patients had increased VCAM-1 content in the BA wall (p = 0.026) but not in the PA wall." (PMID 31485240, 2019). "Asthma patients had increased VCAM-1 content in the BA wall (p = 0.026) but not in PAs." (PMID 31485240, 2019). "Furthermore, they also demonstrated that VCAM-1, but not E-selectin or ICAM-1, is significantly increased in IL-4-positive asthma patients, compared with IL-4-negative asthma patients." (PMID 29614819, 2018).
Obesity (53 papers, 2010 to 2025). Accumulation of substantial excess body fat. "Among spontaneously delivered preterm infants, higher levels of VCAM‐1, an adhesion molecule, were associated with an increased risk of overweight, serving as a robust predictor for overweight and obesity in two instances." (PMID 40346913, 2025). "To consolidate our findings, we established an obesity-associated VCAM1 elevation model via feeding mice with an HFD, and changes in plasma TC, plasma TG, plasma HDL-C, plasma LDL-C, and mouse body weight confirmed the success of the animal model." (PMID 37841916, 2023). "This study reported for the first time the protective role of nuciferine against VCAM1 activation in both obesity-associated mice and human vascular endothelial cells." (PMID 37841916, 2023). "Since inflammation, oxidative stress, and obesity are risk factors for VCAM1 activation and further cardiovascular events, we proposed that nuciferine protects pro-inflammatory factor-induced activation of VCAM1." (PMID 37841916, 2023). "In our study, obesity also increased the expression of vascular cell adhesion molecule-1 (Vcam1), involved in leukocyte adhesion and transendothelial migration." (PMID 39456952, 2024). "After polyunsaturated fatty acid consumption, there would be a correlation between obesity and inflammation, decreasing pro-inflammatory genes and cytokines expression, such as VCAM-1, 8-epi-prostaglandin-F2α (8-EPI), and TNF-α." (PMID 38024342, 2023). "It is also important to note that female mice had nearly half the levels of VCAM-1 when compared to male mice, and it is possible that with a more severe obesity phenotype there would have been a comparable decrease in plasma VCAM-1 between males and females." (PMID 36504827, 2022). "Endurance exercise intervention (ApoE WD EX) significantly alleviated atherosclerotic syndrome by reducing obesity, significantly inhibiting VCAM-1, MCP-1, TNF-α, and IL-1β expression, and increasing the production of SCFAs." (PMID 35256637, 2022). "Genes associated with leukocyte migration, such as Alcam, Icam1, Pecam1 and Vcam1, were induced in brain art ECs by sustained obesity." (PMID 36400935, 2022). "Relative to other brain ECs, art ECs showed enriched expression of several leukocyte adhesion genes, and Vcam1, Pecam1, Alcam and Icam1 were upregulated in art ECs in obesity." (PMID 36400935, 2022). "In our study, we reveals compatible findings in that, compared to ICAM-1 and VCAM-1, E-selectin is more influenced by obesity." (PMID 31550292, 2019). "In 3T3-L1 adipocytes, we evaluated the effect of organotins on the expression of inflammatory response-related genes such as Lgals9, Fn1, Dcn, Vcam1 and S100a8, which are accordingly related to obesity and insulin resistance." (PMID 28824431, 2017). "That said, we have not found any evidence in the literature of an increase in VCAM-1 levels in subjects with obesity after diet-induced weight loss." (PMID 39061938, 2024). "Other studies have suggested that Vcam1 could be a marker for transitional obesity and diabetic nephropathy." (PMID 36118693, 2022). "Additionally, animals fed a HFD exhibit high levels of mRNA expression coding ICAM-1 and VCAM-1 adhesion molecules, which are responsible for the recruitment of M1 macrophages to adipose tissue during obesity." (PMID 32774333, 2020). "PAI-1 and VCAM-1 levels were correlated with clinical indicators of obesity and overweight." (PMID 23113882, 2012). "Obesity mostly upregulated DEGs in endothelial cells for pathways regulating endothelial permeability such as focal adhesion (Prkcb and Vegfc), adherens junction (Pard3), leukocyte transendothelial migration (Prkcb and Vcam1), and Rap1 signaling (Pard3, Prkcb, and Vegfc)." (PMID 39456952, 2024).
Obesity (continued). "Additionally, the increased stimulation of adhesion molecules, such as VCAM-1 in OZRs demonstrated the presence of endothelial activation and dysfunction strictly correlated with inflammation, as reported in subjects affected by the MetS, and obesity." (PMID 32188150, 2020). "Adiponectin acts to prevent vascular dysfunction due to obesity by inhibiting ICAM-1 and VCAM-1 expressions." (PMID 37822716, 2023). "The significance of inflammation-driven inhibition of beige adipogenesis in obesity has been highlighted by studies of the interaction between α4-integrin receptor on pro-inflammatory macrophages and VCAM-1 (vascular cell adhesion molecule-1) on adipocytes." (PMID 32265845, 2020). "Serum VCAM-1, ICAM-1 and E-selectin concentrations are elevated in obesity, chronic renal failure, in lean and obese subjects genetically predisposed to T2DM and in T2DM." (PMID 20158910, 2010). "In children and adolescents, VCAM-1 was elevated with obesity regardless of NAFLD diagnosis compared to age-matched lean controls." (PMID 31291245, 2019). "In male mice, obesity induced by HF-HSD administration was associated with higher plasma glucose, insulin, monocyte chemoattractant protein-1 (MCP-1), and vascular cell adhesion molecule 1 (VCAM-1), but not IL-6 concentrations." (PMID 39861371, 2025). "Although the mechanisms by which obesity inhibits UCP1 expression remain unclear, a role of inflammation has recently been proposed, since integrin alpha 4 (ITGA4)- and VCAM-1 mediated macrophage-adipocyte interactions were found to inhibit UCP1 expression by ERK1/2 and p38 pathway blockade." (PMID 30618796, 2018).
metabolic syndrome (51 papers, 2007 to 2025). A cluster of metabolic risk factors for CARDIOVASCULAR DISEASES and TYPE 2 DIABETES MELLITUS. "As a complement to genetically caused dyslipidemia, we also explored the effects of high fat diet on VCAM-1 expression in retinal vessels." (PMID 20856927, 2010). "In metabolic syndrome, bio-enhanced curcumin formulations have consistently improved lipid profiles but have shown variable effects on endothelial biomarkers such as VCAM-1, intercellular adhesion molecule-1 (ICAM-1), and flow-mediated dilation." (PMID 41302164, 2025). "In another study, strawberry alone reduced LDL cholesterol as well as vascular cell adhesion molecule-1 (VCAM-1) levels in patients with metabolic syndrome." (PMID 36834497, 2023). "Generally, ginger and its constituents are effective agents in the treatment of metabolic syndrome by reducing lipid accumulation by increasing the level of eNOS protein, VCAM1, TNFα, and ENaC." (PMID 35949312, 2022). "In our model of metabolic syndrome, Vcam-1 mRNA expression showed a strong trend to be reduced by LIRA in the kidney but not in the myocardium." (PMID 32093680, 2020). "The FFHR experimental model presents metabolic syndrome criteria, vascular and cardiac remodeling, vascular inflammation due to increased expression of NF-kB, VCAM-1, and pro-atherogenic cytokines." (PMID 25184237, 2014). "Cardiovascular risk factors such as high glucose and dyslipidemia activate the vascular endothelium to secrete inflammatory chemokines (MCP1 and IL8) and adhesion molecules (ICAM1, VCAM1, and E-Selectin), which leads to monocyte binding to the vasculature and the subsequent vascular inflammation." (PMID 37627522, 2023). "We investigate adiponectin ICAM-1, VCAM-1, and metabolic syndrome (MetS) in obese adolescents." (PMID 37822716, 2023). "Muet al (2015) had proven this hypothesis by examining VCAM-1 expression in aortic tissue of dyslipidemia patients." (PMID 38046985, 2021). "Given the strong correlation of postprandial VCAM-1 expression with fasting markers of dyslipidemia, we evaluated whether the composition of TGRL in fasting subjects was also predictive of the postprandial VCAM-1 response." (PMID 31209255, 2019). "HDL cholesterol and oxidized LDLs improved after 250 and 500 mL cranberry juice consumption, while systolic blood pressure and plasma ICAM-1 and VCAM-1 concentrations decreased only at the highest dose, with a stronger effect in the subset of subjects with Metabolic Syndrome." (PMID 27706020, 2016). "We did not measure insulin levels and neither evaluated homeostasis model assessment of insulin resistance index (HOMA IR), which could be helpful in establishing the presence of metabolic syndrome, what could explain variations in VCAM-1 levels." (PMID 23113882, 2012). "Increase of VCAM-1 expression is a multifactorial process, smoking could not increase VCAM-1 independently without other risk factors such as dyslipidemia." (PMID 38046985, 2021). "In women with metabolic syndrome, the consumption of freeze-dried strawberries (FDS) for 8 weeks decreased LDL and vascular cell adhesion molecule 1 (VCAM-1), and similar were the results in another cohort with T2DM female patients." (PMID 33499118, 2021). "Together these data confirm that VCAM-1 upregulation in HAEC and in the circulating plasma are faithful inflammatory biomarkers that correlate with clinical measurers of dyslipidemia and metabolic dysregulation in the subject cohort." (PMID 31209255, 2019). "In female patients with metabolic syndrome, 4 cups of freeze-dried strawberries (FDS) consumed daily for 8 weeks, decreased LDL-cholesterol and the levels of vascular cell adhesion molecule 1 (VCAM-1)." (PMID 30597847, 2018). "Our results showed that apoE-/- mice receiving vehicle alone developed severe atherosclerotic lesions and dyslipidemia, with significantly up-regulated levels of IL-6, TNF-α, VCAM-1 and MCP-1." (PMID 24621517, 2014).
metabolic syndrome (continued). "In a randomized trial of 92 adults with metabolic syndrome, EGCG (400 mg/day for 8 weeks) increased the abundance of Lactobacillus rhamnosus and Bifidobacterium breve, with concurrent reductions in zonulin and VCAM-1." (PMID 41302164, 2025). "Additionally, female patients with metabolic syndrome, who consumed 4 cups of freeze-dried strawberries daily for 8 weeks experienced lower levels of LDL cholesterol and VCAM-1." (PMID 41156509, 2025). "Irisin inhibits the levels of cell adhesion molecules (CAMs), such as intercellular adhesion molecule 1 (ICAM-1), vascular cell adhesion protein 1 (VCAM-1), and E-selectin, which are elevated by dyslipidemia and reduces leukocyte and monocyte adhesion to the arterial wall surface." (PMID 38029393, 2023). "Curcumin, a flavonoid that is mainly found in turmeric, curry spice, and ginger, has been shown to decrease SOD, malondialdehyde (MDA) and CRP in patients with metabolic syndrome and IL-1β, TNF-α, ICAM-1 and VCAM-1 in mice, through the inhibition of the TLR4 signaling pathway." (PMID 33499118, 2021). "An 8-week randomized, controlled trial on 27 subjects with Metabolic Syndrome receiving two cups of a strawberry beverage (composed of 25 g of freeze-dried strawberry powder each) daily for eight weeks, documented a reduction of total and LDL-cholesterol, small LDL particle size, and VCAM-1." (PMID 27706020, 2016). "In contrast to VCAM-1, changes in ICAM-1 surface expression did not correlate with any clinical indicators of dyslipidemia." (PMID 31209255, 2019). "Overall, the current meta-analysis demonstrated that vitamin D supplementation to patients with metabolic syndrome and related disorders resulted in an improvement in vWF, but did not affect ICAM-1, VCAM-1, E-selectin and endothelin levels." (PMID 30519274, 2018).